PPP2R1B (protein phosphatase 2 scaffold subunit Abeta)
Description:
The PR65 subunit of protein phosphatase 2A serves as a scaffolding molecule to coordinate the assembly of the catalytic subunit and a variable regulatory B subunit.
Synonyms: PR65B; PP2A-Abeta
Tractability: Antibody: the Human Protein Atlas places it where antibodies can reach. PROTAC: ubiquitination databases record sites on it; its protein half-life has been measured.
Gene: Protein-coding gene on chromosome 11 (111,726,908 to 111,766,658, reverse strand). Ensembl gene ENSG00000137713.
Subcellular location (Human Protein Atlas): Cytosol; Plasma membrane
Pathways (Reactome):
Signal Transduction: Beta-catenin phosphorylation cascade; DARPP-32 events; Degradation of beta-catenin by the destruction complex; Disassembly of the destruction complex and recruitment of AXIN to the membrane; ERK/MAPK targets; ERKs are inactivated; Negative regulation of MAPK pathway; PI5P, PP2A and IER3 Regulate PI3K/AKT Signaling; RAF activation; RHO GTPases Activate Formins
Cell Cycle: Amplification of signal from unattached kinetochores via a MAD2 inhibitory signal; Cyclin A/B1/B2 associated events during G2/M transition; Cyclin D associated events in G1; EML4 and NUDC in mitotic spindle formation; Inhibition of replication initiation of damaged DNA by RB1/E2F1; MASTL Facilitates Mitotic Progression; Mitotic Prometaphase; Resolution of Sister Chromatid Cohesion; Separation of Sister Chromatids
Disease: APC truncation mutants have impaired AXIN binding; AXIN missense mutants destabilize the destruction complex; CTNNB1 S33 mutants aren't phosphorylated; CTNNB1 S37 mutants aren't phosphorylated; CTNNB1 S45 mutants aren't phosphorylated; CTNNB1 T41 mutants aren't phosphorylated; Signaling by GSK3beta mutants; Truncations of AMER1 destabilize the destruction complex
Immune System: Co-inhibition by CTLA4; Co-stimulation by CD28; PKR-mediated signaling
Metabolism: PP2A-mediated dephosphorylation of key metabolic factors; Regulation of glycolysis by fructose 2,6-bisphosphate metabolism
Cellular responses to stimuli: Turbulent (oscillatory, disturbed) flow shear stress activates signaling by PIEZO1 and integrins in endothelial cells
Hemostasis: Platelet sensitization by LDL
Gene Ontology:
Molecular function: protein binding; protein phosphatase regulator activity
Biological process: apoptotic process involved in morphogenesis; positive regulation of extrinsic apoptotic signaling pathway in absence of ligand; meiotic sister chromatid cohesion, centromeric; spindle assembly
Cellular component: extracellular exosome; membrane raft; protein phosphatase type 2A complex; glutamatergic synapse; synapse
Genetic constraint (gnomAD): Loss-of-function variants: 58 observed, 75.56 expected, observed/expected ratio (o/e) 0.77, 90% interval 0.62 to 0.95. The upper end of that interval is the gene's LOEUF score, 0.95, which puts it in group 4 of 6, group 1 being the genes least tolerant of losing a copy. Missense variants: 695 observed, 765.87 expected, observed/expected ratio (o/e) 0.91, 90% interval 0.85 to 0.97. Synonymous variants: 255 observed, 278.19 expected, observed/expected ratio (o/e) 0.92, 90% interval 0.83 to 1.02.
Homologues: Orthologues: chimpanzee PPP2R1B (99% identical), macaque PPP2R1B (99% identical), rabbit PPP2R1B (97% identical), pig PPP2R1B (96% identical), dog PPP2R1B (96% identical), mouse Ppp2r1b (96% identical), rat Ppp2r1b (96% identical), guinea pig PPP2R1B (95% identical), tropical clawed frog ppp2r1b (86% identical), zebrafish ppp2r1bb (86% identical), zebrafish ppp2r1ba (86% identical), Drosophila melanogaster Pp2A-29B (70% identical). Paralogues in human: PPP2R1A (84% identical), PPP4R1 (26% identical).